AFP (alpha fetoprotein)
Diseases named in the same sentence as AFP in open-access papers (continued):
Sharing a sentence is not in itself a finding about the gene and the disease.
tumor (continued). "Baseline tumor factors, including the BCLC stage and AFP level, which reflect biological features of HCC, and liver function assessed using the Child–Pugh score predicts OS after TACE." (PMID 30974843, 2019). "summarizes the descriptive statistics and comparisons of the NLR ratio, PLR ratio and CRP levels for each of the 4 tumour characteristics of MTD, AFP, multifocality and PVT patient groups." (PMID 30662766, 2019). "Nowadays, a biopsy is generally not attempted in patients with typical radiographic findings and elevated tumor markers such as beta-human chorionic gonadotropin (β-HCG) and alpha fetoprotein (AFP)." (PMID 32922913, 2019). "The results suggested that tumor size, TNM stage, treatment exposure, and serum AFP level are significantly correlated with ACR." (PMID 31164099, 2019). "The C-index was 0.644, 0.638, 0.597, and 0.546 by tumor size, AFP, MVI, and incomplete tumor capsule, respectively, which were significantly lower than that by the nomogram (P < 0.001 for each comparison)." (PMID 31179237, 2019). "Variables such as age, gender, status of HBV infection, AFP, AST, ALT, PLR, NLR, tumor differentiation, satellite lesions, Ishak score tumor number, tumor size, surgery type and blood transfusion were included in PSM analysis." (PMID 29530006, 2018). "AFP is a frequently-used tumor biomarkers for the diagnosis and predicting prognosis of HCC, and monitoring metastasis and relapse in HCC patients with high AFP level after hepatectomy." (PMID 29348394, 2018). "When AFP was silenced in PLC/PRF/5 cells, cell proliferation, tumour growth, migration and invasion were inhibited, and the numbers of S-phase and apoptotic cells were increased." (PMID 30301886, 2018). "Variables included in the analysis were serum iron levels, AFP levels, HBV- related HCC tumor size, BCLC stages, and antiviral therapy timing." (PMID 29467672, 2018). "The patients without tumors (Cyst and Stone) had normal level of alpha-fetoprotein (AFP), Carcinoembryonic antigen (CEA) and carbohydrate antigen 19–9 (CA19-9), which is used as markers for tumor diagnosis." (PMID 29459779, 2018). "LMR < 4.01, AFP ≥ 400 ng/mL, BCLC stage B or C, multiple tumors, tumor size ≥ 5 cm, incomplete tumor capsule, NLR ≥ 2.78 and PLR ≥ 99.5 were also found to be significantly associated with poor DFS." (PMID 29416061, 2018). "In our report, during the initial diagnostic, LDH was increased in all of the cases in relation to the metastasis and tumour burden, in two patients with HCG and in one with AFP." (PMID 30792805, 2018). "His tumor marker levels were carcinoembryonic antigen (CEA), 81.5 ng/ml; carbohydrate antigen (CA) 19-9, 28 U/ml; α-fetoprotein (AFP), 5.0 ng/ml; and protein induced by vitamin K absence or antagonists-II (PIVKA-II), 14 mAU/m." (PMID 29721707, 2018). "The prognosis of HBV- related HCC patients with serum iron levels <15.1 μmol/l together with higher AFP levels, worse BCLC stages, and larger tumor lesion were poor." (PMID 29467672, 2018). "We found that low FABP4 expression was significantly correlated with Alb (P = 0.038), AFP level (P = 0.007), CA19‐9 (P = 0.048), PVTT (P = 0.016), tumor size (P = 0.018), and encapsulation (P = 0.022)." (PMID 29733540, 2018). "And we the Alb, AST, AFP, GGT, HBsAg, PVTT, number of tumor, micro metastasis, encapsulation, MVI, BCLC, FABP4 expression were correlated with OS of HCC patients." (PMID 29733540, 2018). "In the analysis with clinicopathological variables, hsa-miR-210 showed a close correlation with AFP, pathological grade, TNM stage, tumor stage and vascular invasion." (PMID 30560088, 2018). "Tumor markers (CEA, CA 19–9, PSA) were normal, except for the AFP levels (202.7 ng/ml).A biopsy of a subcutaneous nodule showed focal fat necrosis with liquefaction phenomena of adipocytes, ghost-like cells and calcium deposits consistent with PP." (PMID 29301491, 2018).
tumor (continued). "In 7 of 29 patients (24.1%) with reported cases of tumor markers in liver IPT, carbohydrate antigen 19-9 was elevated and AFP was elevated in 2 of 58 patients (3.4%)." (PMID 30203247, 2018). "On the contrary, AFP contributes to the promotion of the change of CD4+ T and CD8+ T cell proportion and leads to tumor immune escape." (PMID 29805966, 2018). "In contrast, alpha fetoprotein (AFP), which is the main tumor marker that arises in presence of HCC, is inadequate to be used in the screening process due to its low sensitivity and specificity." (PMID 30562917, 2018). "Serum tumor marker levels were increased to 8.8 ng/ml in CEA (normal range ≤ 5.0 ng/ml) and 28.3 ng/ml in AFP (normal range ≤ 7.0 ng/ml)." (PMID 30191347, 2018). "AFP expression levels were higher in AMC-H2 than in AMC-H1; yet, the AMC-H1 donor showed much higher serum AFP levels at the time of tumor resection than the AMC-H2 donor." (PMID 29801504, 2018). "Next, there was significant difference in clinicopathological factors of blood concentration of AFP and PIVKA-II, size of tumor, and grade of portal vein infiltration between the DEPDC5-negative and -positive groups." (PMID 29311600, 2018). "Tumour size > 7 cm (p < 0.001), presence of AEN (p = 0.03), ITN (p = 0.02), AFP > 400 ng/ml (p = 0.01) and radiologic response (p < 0.001) were found to be prognostic on univariate analysis." (PMID 29463228, 2018). "Focused on tumor markers, des-gamma carboxyprothrombin (DCP) was high while alpha-fetoprotein (AFP) and lectin-reactive alpha-fetoprotein (AFP-L3%) were within normal limits." (PMID 30003446, 2018). "According to a report on tumor markers in liver IPT, CA 19-9 was elevated in 7 of 29 patients (24.1%) and AFP was elevated in 2 of 58 (3.4%)." (PMID 30203247, 2018). "Previous studies have reported that tumor markers can be helpful in raising the possibility of a cHCC-CC tumor, where both CA19.9 and AFP can be elevated." (PMID 29486800, 2018). "A logistic regression model of PVT showed significance for several single parameters as continuous variables, but when all parameters were considered together, there was significance in the final model for tumor multifocality, MTD, AFP, ALKP, and albumin." (PMID 30009156, 2018). "Prognostic factors such as tumor stage and tumor markers [e.g., prostate-specific antigen (PSA), alpha-fetoprotein (AFP), human chorionic gonadotropin (hCG)] have been shown to correlate with the course of disease and/or prognosis." (PMID 29896113, 2018). "The C-index of the PON1-related nomogram was 0.714, thus indicating a more effective predictive performance than the 7th American Joint Committee on Cancer (AJCC) tumor stage (0.534), AJCC T stage (0.565), or alpha-fetoprotein (0.488)." (PMID 30477582, 2018). "As a result, alpha‐fetoprotein (AFP) and carbohydrate antigen 19‐9 (CA19‐9) are regarded as the optimal serum tumor markers for HCC and ICC, respectively." (PMID 29473340, 2018). "What's more, high expression of has-miR-210 portends high AFP level, pathological grade, TNM stage and tumor stage, which verified the essential role of hsa-miR-210 in influencing the degree of tumor malignant." (PMID 30560088, 2018). "Real time qPCR analyses of alpha fetoprotein (AFP), HCC tumor marker, showed a reduced expression in all treated groups compared to the control, with a much stronger effect in the combination group (p=0.0138)." (PMID 29541403, 2018). "The univariate analysis revealed that the AST, AFP, GGT, ALP, PVTT, tumor size, micro metastasis, encapsulation, MVI, BCLC, and FABP4 expression were correlated with RFS of HCC patients." (PMID 29733540, 2018). "High RBBP5 expression was significantly correlated with high serum level of AFP (P = 0.019), advanced TNM stage (P = 0.019), larger tumor size (P = 0.012), and high Ki-67 expression (P < 0.001)." (PMID 30533424, 2018).
tumor (continued). "They believed that a preoperative CTC count of ≥2 is a novel predictor for tumor recurrence in HCC patients after surgery, especially in patient subgroups with AFP levels of ≤400 ng/ml." (PMID 30176913, 2018). "Four weeks after the operation, serum tumor marker levels had decreased to 1.2 ng/ml in CEA and 1.6 ng/ml in AFP." (PMID 30191347, 2018). "The well-known and most frequently used tumor markers for tumor diagnosis, such as CA19-9 and AFP, have their limitations." (PMID 29459779, 2018). "In univariate analysis, levels of AST, ALB, ALP, CRP, AFP, and NLR, tumor size, tumor number, metastasis, vascular invasion, antiviral therapy, and TACE with H101 were significantly associated with OS." (PMID 28728568, 2017). "Parameters with gradual increment from BCLC stage 0 to stage D were serum bilirubin (p< 0.001), international normalized ratio (INR) (p< 0.001), serum alpha-fetoprotein (AFP) level (p< 0.001), platelet count (p< 0.001), and total tumor volume (p< 0.001)." (PMID 28333991, 2017). "On the other hand, significant increase in tumor markers, CEA and AFP was in agreement with previous studies." (PMID 28240047, 2017). "After treating the continuous variables, including levels of AFP, ALB, and ALP, and tumor size, as dichotomous variables, significant independent risk factors were integrated to develop the nomogram for predicting the OS of the study cohort." (PMID 28728568, 2017). "A further cohort of 59 patients (84.3%) were screened for serum tumor markers, including NSE, AFP, CEA, CA125, CA153, CA199, CA724, and CY211; 26 positive cases (44.1%) were identified." (PMID 29180979, 2017). "We also found that patients with low level of PHD1 tend to have incomplete tumor encapsulation, however, patients with higher PHD2 level are more often to have higher serum AFP." (PMID 28099905, 2017). "When antigens (tumor markers: carcinoembryonic antigen (CEA) and alpha-fetoprotein (AFP)) are present in the system, immunocomplexes with antibodies in Ag-3DOCs are formed." (PMID 30965852, 2017). "To further investigate the anti-tumor activity of HN3-mPE24, we measured the concentration of serum alpha-fetoprotein (AFP) near the end of the treatment." (PMID 27419635, 2017). "Tumor size, tumor relapse, BCLC stage, and AFP were considered to be important predictors of tumor recurrence." (PMID 29029437, 2017). "Diagnosis of GCT involves the measure by immunoassays of a set of biochemical tumour markers including β-HCG, AFP and LDH and LD-1." (PMID 29262668, 2017). "Tumor markers were also determined: human chorionic gonadotrophin (β-HCG), alpha fetoprotein (AFP), and LDH." (PMID 28514960, 2017). "The NAFLD group presented with significantly larger tumours (P = 0.009), whilst HCV patients had a higher alpha fetoprotein (P = 0.018)." (PMID 27634970, 2017). "Of all variables included in the nomogram, AFP level before TACE, tumor size, metastasis, and vascular invasion were previously recognized as prognostic factors of patients with intermediate to advanced HCC." (PMID 28728568, 2017). "In univariate analysis, the elevated serum AFP (P < 0.001) and hs-CRP (P = 0.007) levels, AJCC 7th edition (P = 0.002), incomplete encapsulation of the tumor (P = 0.009), and MVI (P < 0.001) were identified as significant predictors for RFS." (PMID 28296727, 2017). "We performed a linear correlation analysis and showed that D-dimer levels were positively correlated with the rates of change in tumor diameter, PVTT diameter, and AFP." (PMID 29246017, 2017). "Alpha-fetoprotein (AFP) and protein induced by vitamine K absence or antagonist-II (for the latter, using [PIVKA II]) are widely used as tumor markers for detection of HCC." (PMID 28035063, 2017). "Univariate analysis showed that age, gender, tumor size, hepatic virus infection, ALT, pre-AFP, pre-PIVKA-II, and GPC3 expression by immunohistochemical staining were not significant risk factors for recurrence." (PMID 28035063, 2017).
tumor (continued). "After analysis using the stratification method, prognostic significance of PHD3 was found in HCC patients with a single tumor, tumor size > 5 cm, HBV(+), AFP ≤ 20 μg/l, Edmondson stage I–II or BCLC stage 0+A." (PMID 28099905, 2017). "Fib was correlated with Child-pugh stage, alpha-fetoprotein (AFP), size of largest tumor, macro- and micro-vascular invasion." (PMID 27935864, 2017). "We previously established the AP-factor, a product of the serum levels of AFP and PIVKA-II, as a critical marker for preoperatively predicting tumor malignancy." (PMID 28830473, 2017). "F-M, H-M and FPHA-M models exhibited significantly increased positive rates than P-M for HCC, including different levels of elevated serum AFP, BCLC stages and tumor sizes." (PMID 29228649, 2017). "Serum alpha-fetoprotein (AFP), hyper-sensitive C-reactive protein (hs-CRP), incomplete tumor encapsulation, and double positive staining of Cytokeratin 7 and Cytokeratin 19 on tumor cells were identified as independent predictors for OS." (PMID 28296727, 2017). "Mice were monitored for tumor growth using bioluminescence imaging (BLI), magnetic resonance imaging (MRI), and measurement of serum levels of human α-fetoprotein (AFP)." (PMID 29259231, 2017). "The results of the chi-square test indicated that abnormal expression of GABPA in HCC tissues was related to alpha-fetoprotein (AFP) levels (P = 0.001), tumor grade (P = 0.017), and tumor distant metastasis (P = 0.021)." (PMID 28549418, 2017). "Our study indicates that the early stages [tumor, node, and metastasis (TNM) stage I and II] of HCC can be diagnosed using the combination of AFP and FN1 through a routine blood test." (PMID 28842594, 2017). "We analyzed the correlation between subtype and clinicopathologic features, and further investigated the expression of AFP, vascular endothelial growth factor (VEGF), and CEA in these tumor tissues using immunohistochemistry." (PMID 28423604, 2017). "Correlation analyses showed that INTS6 expression was significantly correlated with serum alpha-fetoprotein levels (AFP, p =0.004), pathology grade (p =0.005), and tumour recurrence (p =0.04)." (PMID 28899352, 2017). "Univariate analysis showed preoperative Fib, AFP, NLR, size of largest tumor, tumor number, macro- and micro- vascular invasion were significantly associated with disease-free survival (DFS) and overall survival (OS) in HCC patients with liver transplantation." (PMID 27935864, 2017). "However, the most important advantage of combining morphological tumor characteristics with serum alpha-fetoprotein concentration is to provide data on high-risk, rather than to identify all patients with microvascular invasion, and the presented model was created solely to evaluate such capability." (PMID 28057916, 2017). "Early diagnosis of AFP, TPA, AFU and so on in a series of tumor markers (in fact, the majority of patients in the middle or late stage of cancer) cannot be timely and accurate." (PMID 29093570, 2017). "AFP is a tumor marker for hepatocellular carcinoma and yolk sac tumor, and PSA is a tumor marker for early detection of prostate cancer." (PMID 29168770, 2017). "Due to lack of radioghraphic characteristics, diagnosis of intracranial germinoams mainly depends on the levels of tumor markers such as β-human chorionic gonadotropin (β-HCG) and α-fetoprotein (AFP) in serum and cerebrospinal fluid (CSF)." (PMID 26771195, 2016). "Seven risk factors provided a significant influence on prognosis, prior hepatectomy: BCLC stage, and tumor factor: vascular invasion, tumor diameter, and before PA-TACE: platelet count, HBV-DNA level, AFP level and Child-Pugh score change." (PMID 27506942, 2016). "An immunoassay for the detection of two important tumour markers, carincoembryonic antigen (CEA) and alpha-fetoprotein (AFP)." (PMID 27690118, 2016). "The plasma miR-224 level was more sensitive to the presence of smaller tumors than were conventional tumor markers, such as PIVKA-II and AFP." (PMID 27462777, 2016).
tumor (continued). "In building the model, four main prognostic factors were selected: ITA.LI.CA tumor staging, ECOG PST, CPS, and AFP." (PMID 27116206, 2016). "Serum CA19-9 levels correlated with gender, age, and tumor depth (all P<0.05); AFP levels correlated with pathological type (P=0.005); and CA125 levels correlated with gender, tumor size, pathological type, tumor depth and lymph node metastasis (all P<0.05)." (PMID 27533455, 2016). "Six (AFP, CEA, CA19-9, CYFRA21-1, SCC, and PSA) and 7 (AFP, CEA, CA19-9, CYFRA21-1, SCC, CA125, and CA15-3) tumour markers were measured for the men and women, respectively." (PMID 27355357, 2016). "The levels of AFP and CEA cancer markers were elevated in tumor rats as compared to normal control (p < 0.05)." (PMID 27187346, 2016). "Section 6 highlights the key applications of DELBA for the ultrasensitive in vitro detection of several important tumor markers including carcinoembryonic antigen (CEA), prostate specific antigen (PSA), and alpha‐fetoprotein (AFP)." (PMID 27980996, 2016). "MAGL protein levels (MAGL IOD value), A-fetoprotein (AFP), tumor, node and metastasis (TNM) stage were significantly correlated to the degrees of tumor differentiation (p < 0.05)." (PMID 27767105, 2016). "Because AFP is a surrogate biomarker in HCC diagnostics, we performed AFP ELISA to monitor the concentration of AFP, used as an indicator for monitoring orthotopic HCC tumor growth, in orthotopic HCC-tumor-bearing mice." (PMID 27502492, 2016). "Finally, we are concerned about the necessity of annual surveillance of the patient, which could consist of clinical examination, U/S examination of the upper and lower abdomen and the scrotum, chest X-ray, and specific tumor markers (AFP, LDH, CEA, and b-HCG)." (PMID 28003830, 2016). "Many patients with NSGCT have elevated serum tumor markers, such as lactate dehydrogenase (LDH), alpha-fetoprotein (AFP), and human chorionic gonadotropin (hCG)." (PMID 27150447, 2016). "Parameters such as vascular invasion, poor differentiation, tumor size >5 cm, number of lesions, HCC exceeding the Milan criteria, and elevated pretransplant AFP levels have been reported to have significant impact on the rate of posttransplant recurrences." (PMID 27034867, 2016). "Multivariate analysis identified two significant prognosticators (levels of alpha fetal protein [AFP] and gamma-glutamyl transpeptidase [GGT]) of RFS and five significant prognosticators (tumor number, tumor size, AFP, GGT and recurrence type) of OS." (PMID 27620527, 2016). "For this reason, we integrated the ITA.LI.CA tumor staging with CPS, ECOG PST, and AFP in a multivariable survival model to construct the ITA.LI.CA prognostic system." (PMID 27116206, 2016). "Prognostic factors evaluated by univariate and multivariate analyses included gender, age, AFP, BCLC stage, CTP class, BED10, EQD2, tumor size and TAE/TACE." (PMID 27809890, 2016). "A univariate analysis revealed that the gender, tumor size, Edmondson grade, micro-vascular invasion, macro-vascular invasion, pathological satellite, encapsulation, TNM stage, BCLC stage, AFP and EIF3H expression were significantly correlated with RFS or OS." (PMID 27340783, 2016). "The main tumor markers of interest are carbohydrate antigen 19–9(CA19-9) and α -fetoprotein (AFP), which are useful adjuncts to imaging in patients with CC and HCC respectively." (PMID 26917546, 2016). "The expression level of TIP30 in HCC was inversely correlated with serum alpha‐fetoprotein (AFP) levels, HBV infection, and tumor differentiation." (PMID 27418384, 2016). "In Alberta, since 2007, we have been transplanting HCC patients using a total tumour volume (TTV) of ≤115 cm3 and alpha-fetoprotein (AFP) ≤400 ng/mL as selection criteria." (PMID 27446823, 2016). "By IHC, we confirmed upregulation of AFP, FOXA2 and EOMES in a subset of cells morphologically appearing differentiated within TCam-2-ΔSOX2 tumor tissues." (PMID 27283990, 2016).